CYP2E1 (cytochrome P450 family 2 subfamily E member 1)
Diseases named in the same sentence as CYP2E1 in open-access papers (continued):
Sharing a sentence is not in itself a finding about the gene and the disease.
COVID-19 (4 papers, 2022 to 2023). A disease caused by infection with severe acute respiratory syndrome coronavirus 2. "CYP2E1 genes might be activated by inflammatory cytokines of COVID-19 via NF-κB pathway, but the underlying ROS production would not be alleviated by the inhibited Nrf2 signaling." (PMID 35979235, 2022). "Licorice is one of the most frequently involved herbs in these herbal formulae or preparations against COVID-19, increasing risk for HDIs for anti-COVID-19 drugs, and has been reported to modulate several CYP isoforms in vitro, including CYP3A4, CYP2C9, and CYP2E1." (PMID 37502215, 2023).
dilated cardiomyopathy (4 papers, 2017 to 2024). Cardiomyopathy which is characterized by dilation and contractile dysfunction of the left and right ventricles. "There was also an upregulation in the expression of CYP2E1 in the hearts affected by dilated cardiomyopathy in cTnTR141W transgenic mice." (PMID 39188949, 2024). "Cyp2e1 inhibition increases oxidative stress and apoptosis of cardiomyocyte in a murine dilated cardiomyopathy model and Cyp2e1 inhibition reduces cardiomyocyte apoptosis." (PMID 30213070, 2018). "Pharmacological inhibition and genetic knock down of Cyp2e1 have been shown to confer cardioprotection in a DOX-induced dilated cardiomyopathy mouse model by inhibiting oxidative stress and apoptosis." (PMID 28078076, 2017).
nasopharyngeal carcinoma (4 papers, 2010 to 2021). A carcinoma arising from the nasopharyngeal epithelium. "Although numerous studies have examined the association of the polymorphisms for CYP2E1, GSTP1, MPO and NQO1 genes with various tumors, very few have investigated the associations between variants of these genes and the risk of nasopharyngeal carcinoma." (PMID 20663217, 2010).
pulmonary fibrosis (4 papers, 2021 to 2025). Chronic progressive interstitial lung disorder characterized by the replacement of the lung tissue by connective tissue, leading to progressive dyspnea, respiratory failure, or right heart failure. "It has been demonstrated that the upregulation of Cyp2e1 is involved in pulmonary fibrosis via ER stress- and ROS-dependent mechanisms." (PMID 40021627, 2025).
acute liver failure (3 papers, 2012 to 2021). Rapid deterioration of liver function causing encephalopathy and coagulopathy. "APAP-mediated acute liver failure is initiated by its reactive metabolite, NAPQI, usually catalysed by hepatic CYP2E1 enzyme." (PMID 23272189, 2012).
acute lymphoblastic leukemia (3 papers, 2018 to 2025). Leukemia with an acute onset, characterized by the presence of lymphoblasts in the bone marrow and the peripheral blood. "Genotype and alleles frequency of NAT2, NQ01, and CYP2E1 polymorphisms in children with acute lymphoblastic leukemia and controls." (PMID 33072605, 2020). "Gene-gene interaction analysis between NAT2, NQ01, and CYP2E1 polymorphisms and acute lymphoblastic leukemia risk." (PMID 33072605, 2020). "Additionally, the CYP2E1*5 allele, a variant associated with CYP2E1 gene polymorphisms, increases the risk of acute myeloid and lymphoblastic leukemia." (PMID 41249771, 2025).
asthma (3 papers, 2021 to 2024). "Venn diagram analysis revealed 24 genes common for both disorders, including asthma-specific key nodes Timp1, Cyp2e1, and Muc5ac." (PMID 35625754, 2022). "The underlying key genes in asthma pathogenesis and those regulated by treatment including Adipoq, HMOX1, SPP1, Cyp2e1, TNC, MB, MPO, Col9a1, Ckmt2, and Erbb4 were taken as examples to illustrate the positions and relationships with other points and midline in the figure." (PMID 33531915, 2021). "Finally, Cyp2e1 and Cat, DEGs downregulated in analyzed asthma-related GEO datasets, were significantly suppressed both in asthmatic and fibrotic lungs: Cat by 11.2- and 9.6-fold, respectively, and Cyp2e1 by 4.8- and 2.8-fold, respectively, compared with healthy control." (PMID 35625754, 2022). "The most influential nodes (Fn1, Igf1, Ccl2, C3, Timp1, Cxcl12, Ccl4, Ccr2, Spp1, C3ar1, Cat, Cyp2e1, Muc5ac, Muc5b) were selected for further validation in the OVA-induced asthma and post-asthmatic fibrosis murine model." (PMID 35625754, 2022).
colitis (3 papers, 2021 to 2025). Inflammation of the colon. "That meant the expression patterns of Arg2 and Cyp2e1 exhibit high coordination, indicating an intense regulation between them, in the condition of experimental colitis and 2′‐FL administration." (PMID 40501496, 2025). "In the present study, Arg2 and Cyp2e1 were significantly increased in DSS‐induced colitis mice and decreased by 2′‐FL." (PMID 40501496, 2025). "This was consistent with and explained the synchronized upregulation of Arg2 and Cyp2e1 in DSS‐induced colitis in the present study." (PMID 40501496, 2025). "Our current results showed that exposure to 5% DSS significantly elevated the amounts of intestinal iNOS, 3-NT, CYP2E1, and COX-2, whereas EA administration significantly attenuated the elevated levels of these oxidative/nitrative stress marker proteins in DSS-induced colitis mice." (PMID 37891965, 2023).
endometrial cancer (3 papers, 2016 to 2018). Primary or metastatic malignant neoplasm involving the endometrium (mucous membrane that lines the endometrial cavity). "Previously, we investigated the interaction between genetic make-up and acrylamide intake for endometrial cancer risk, and we observed indications for interaction with SNPs in CYP2E1 and the deletions of GSTM1 and GSTT1." (PMID 28391539, 2017). "The observed interaction with these CYP2E1 SNPs contributes to the evidence for a causal association between acrylamide and endometrial cancer risk." (PMID 27713515, 2016). "Based on this study and our study on endometrial cancer, we recommend follow-up of interactions between acrylamide intake and SNPs for ovarian and endometrial cancer risk, particularly SNPs in CYP2E1, GSTs, the HSD3B1/B2 gene cluster, AKR1C1, NQO1, GPX1 and MGC12965." (PMID 28391539, 2017). "However, the nominally statistically significant interaction between acrylamide and SNPs in CYP2E1 contributes to the evidence of a causal association between acrylamide intake and endometrial cancer risk but confirmation is needed." (PMID 27713515, 2016). "In combination with the fact that we only observed an association between acrylamide and endometrial cancer risk in women with at least one copy of GSTM1, this could, in line with the results for the CYP2E1 SNPS, suggest that acrylamide itself is the causative compound in endometrial carcinogenesis." (PMID 27713515, 2016). "Rs2480258 in CYP2E1 that statistically significantly modified the association between acrylamide intake and endometrial cancer risk was not in Hardy-Weinberg equilibrium, although the deviation was minor (p = 0.03) and not statistically significant after adjustment for multiple testing." (PMID 27713515, 2016).
head and neck squamous cell carcinoma (3 papers, 2012 to 2022). A squamous cell carcinoma that arises from any of the following anatomic sites: lip and oral cavity, nasal cavity, paranasal sinuses, pharynx, larynx, and salivary glands. "CYP2E1 C2C2 genotype is significantly associated with advanced clinical stages, and also associated with tumor recurrence, since it is important for determining the parameters associated with tumor progression and poor outcomes in patients with head and neck squamous cell carcinoma." (PMID 22957075, 2012).
hepatoblastoma (3 papers, 2013 to 2023). Hepatoblastoma (HB) is a malignant hepatic tumor and is the most common pediatric liver cancer. "Then we specifically investigated the individual genes that indicate hepatocyte differentiation (Cyp2e1), hepatoblastoma markers (Igf2, Afp, Glul, Krt19) and embryonal hepatoblastoma stem cell markers (Dlk1, Epcam and Gpc3)." (PMID 37414763, 2023). "C3A cells, derived from HepG2 cells, are a human hepatoblastoma cell line that maintains several liver functions but do not express CYP2E1." (PMID 23577625, 2013).
Hyperglycemia (3 papers, 2016 to 2023). An increased concentration of glucose in the blood. "Increased CYP3A4 and CYP2E1 activities have also been reported by us, as well as other researchers in hyperglycemia under diabetic conditions, as well as under in vitro conditions of nutrient overload." (PMID 31443411, 2019).
hyperlipidemia (3 papers, 2014 to 2017). "In experimental rat models of hyperlipidemia combined with cerebral ischemia, reperfusion injury increases the protein expression of CYP2E1 combined with enhanced CYP2E1 protein expression and levels of proinflammatory factors." (PMID 28163821, 2017). "In animals with cerebral induced I/R and hyperlipidemia, CYP2E1 induction exacerbates neurological deficit and increases ROS formation, oxidative stress, inflammation, and neurodegeneration." (PMID 28163821, 2017). "Our study’s model successfully induced visceral obesity, high plasma FFA levels, hyperlipidemia, and liver CYP4A (data not shown) and CYP2E1 expression." (PMID 25520925, 2014).
kidney damage (3 papers, 2021 to 2025). "In addition, apigenin caused suppression of cytochrome P450 2E1 (CYP2E1), phosphorylated necrosis factor kappa B (p-NF-κB p65), and p-p38 MAPK in cisplatin-induced kidney damage." (PMID 34715860, 2021). "Nephropathy is improved via CYP2E1 expression and activity in diabetic rat kidneys, as CYP2E1 activity is capable of creating an oxidative environment and inducing the metabolism of various endogenous and exogenous compounds, ultimately resulting in formation of AGE products and ROS accumulation." (PMID 36699147, 2021).
non-small cell lung carcinoma (3 papers, 2012 to 2024). A group of at least three distinct histological types of lung cancer, including non-small cell squamous cell carcinoma, adenocarcinoma, and large cell carcinoma. "Conversely other studies showednon-significant impact of CYP1A1*2C, CYP1B1*4, CYP2D6*1A, CYP2E1*6, CYP2E1*7B polymorphisms with both platinum and taxane basedchemotherapy response in in non-small cell lung carcinoma patients (CLC-P)." (PMID 40092865, 2024). "In addition, CYP2E1 positivity is closely correlated with a poor survival of patients with non-small cell lung carcinoma, and the expression of CYP2E1 in bronchial epithelium has a prognostic potential." (PMID 22957075, 2012). "CYP2E1 genetic polymorphism affects the susceptibility of multiple tumors, while CSMD3 mutation is significantly linked to prognosis in some cancers such as non-small cell lung cancer, esophageal squamous cell carcinoma, but their specific mechanism still needed further exploring." (PMID 37264314, 2023).
oral cancer (3 papers, 2013 to 2021). "A case-control study of 41 male oral cancer patients and 123 healthy controls found that people with the CYP2E1 c1/c2 or c2/c2 genotype had a higher risk of oral cancer (multicovariate-adjusted OR = 2.0; 95% CI, 0.8–5.4) than those with the c1/c1 genotype." (PMID 23983642, 2013). "In terms of the cytochrome p450 (CYP) metabolism pathway, the polymorphisms of CYP-involved genes (e.g., CYP26B1, CYP1A1, CYP2A6, and CYP2E1) have been found to activate areca nut (AN)-derived nitrosamines, thereby significantly increasing the susceptibility to tobacco-induced oral cancer." (PMID 34422810, 2021). "Finally, a meta-analysis by Guo and colleagues investigated the associations between CYP2E1 Rsal/PstI polymorphisms and the risk of developing oral cancer." (PMID 29342885, 2018). "The CYP2E1 polymorphisms may increase the risk of oral cancer." (PMID 23983642, 2013).
psoriasis (3 papers, 2022 to 2024). An autoimmune condition characterized by red, well-delineated plaques with silvery scales that are usually on the extensor surfaces and scalp. "This is because CYP2E1 is involved in the defense against ROS in healthy skin, whereas this defense is diminished in people with psoriasis." (PMID 38621674, 2024). "Researchers have found that CYP1A1 and CYP2E1 are more highly expressed in the skin of people with psoriasis, both before and after phototherapy, indicating that psoriatic lesions respond differently to oxidant exposure." (PMID 38621674, 2024). "Abnormal expressions of CYP1A1 and CYP2E1, members of the cytochrome P450 (CYP450) family, are closely related to the occurrence and development of psoriasis, which may affect the normal metabolism of ginkgolic acid, thereby leading to a marked elevation in plasma expression levels." (PMID 35463691, 2022).
Sepsis (3 papers, 2012 to 2023). Sepsis is defined as life-threatening organ dysfunction caused by a dysregulated host response to infection. "Notably, these DEPs including Fads2, Fgb, Cypla2, Cyp2e1, Cfb, Serping1, Fgg, Etnppl, Agt, Hsd3b5, Gnmt, A2m, Pck1, Stat3, Ptpn1, Scd1, Slc2a1, and Uox were key genes in liver sepsis, which maybe associated with inflammation in sepsis." (PMID 37255592, 2023). "Cyp2e1 is reported to generate reactive oxygen species (ROS) and reactive nitric oxide (RNS) that contribute to cell dysfunction during sepsis." (PMID 37255592, 2023).
acute kidney injury (2 papers, 2015 to 2020). Sudden and sustained deterioration of the kidney function characterized by decreased glomerular filtration rate, increased serum creatinine or oliguria. "CYP2E1 deletion in mice prevents cisplatin-induced acute kidney injury demonstrating a central role for CYP2E1 in this well-established model of nephrotoxicity." (PMID 33232872, 2020).
adenoma (2 papers, 2005 to 2022). A neoplasm arising from the epithelium. "CYP2E1 was excluded from this comparison, since CYP2E1 expression was only detected in three disease-free controls and two patients with adenoma." (PMID 16281975, 2005). "Expression of CYP2C, CYP2E1, CYP3A4, and CYP3A5 in colon mucosa of normal and adenomatous colonic tissue of patients with adenoma and disease-free controls was determined by RT-PCR." (PMID 16281975, 2005). "However, in normal tissue of patients with adenomas, protein levels of CYP2C8, CYP3A4 and CYP3A5, but not that of CYP2E1, were significantly lower than in biopsies obtained from disease-free controls." (PMID 16281975, 2005).
alcoholic hepatitis (2 papers, 2018 to 2021). Acute hepatitis resulting from ingestion of alcohol. "From the two analyzed cyp genes, cyp4a14 showed to be more involved in the induction of NAFLD and cyp2e1 in alcoholic hepatitis." (PMID 33924115, 2021).
Anxiety (2 papers, 2010 to 2014). Intense feelings of nervousness, tension, or panic often arise in response to interpersonal stresses. "We investigated whether variation in genes encoding cytochrome P450 2E1 (CYP2E1) or acetaldehyde-metabolising enzymes (ALDH1A1, ALDH2) might alter the risk of AD, with and without symptoms of anxiety, in a Cape population with mixed ancestry." (PMID 24567230, 2014).
autoimmune disease (2 papers, 2011 to 2022). A disorder resulting from loss of function or tissue destruction of an organ or multiple organs, arising from humoral or cellular immune responses of the individual to their own tissue constituents. "Among the wide substrate spectrum of CYP2E1, TCE has been implicated in the development of autoimmune disorders and immune system dysfunction both in human and animal studies." (PMID 21281483, 2011).
cardiomyopathy (2 papers, 2021 to 2022). A disease of the heart muscle or myocardium proper. "Similarly, knockdown of cytochrome P450 2E1 (Cyp2e1), another CYPs family, exhibited the restorative roles in oxidative stress-mediated cardiomyopathy." (PMID 35387435, 2022). "Since CYP2E1 and ALDH2 are expressed in the heart, future studies of the opposite regulation of CYP2E1 (i.e., induction) and ALDH2 (i.e., suppression) during the alcohol-mediated production of MDA and/or 4-HNE adducts and the consequent cardiomyopathy would be of interest." (PMID 33568752, 2021).
cervical cancer (2 papers, 2017 to 2022). A primary or metastatic malignant neoplasm involving the cervix. "Association of genotypes of CYP1A1 T>C rs4646903, CYP1A1 A>G rs1048943, CYP2E1 T>A rs6413432, RAD51 G>C rs1801320, XRCC1 G>A, rs25487 XRCC2 G>A rs3218536 and XRCC3 C>T rs861539 polymorphisms with vital status and recurrence of cervical cancer cases (n = 227)." (PMID 35996502, 2022). "Association of genotypes of CYP1A1 T>C rs4646903, CYP1A1 A>G rs1048943, CYP2E1 T>A rs6413432, RAD51 G>C rs1801320, XRCC1 G>A, rs25487 XRCC2 G>A rs3218536 and XRCC3 C>T rs861539 polymorphisms with clinical response of cervical cancer cases (n = 227)." (PMID 35996502, 2022). "Recently, the relationships between some other polymorphisms and cervical cancer development were investigated, such as CYP1A1 MspI (rs4646903), COMT (rs4680), and CYP2E1 (rs3813867) polymorphisms." (PMID 29326607, 2017). "Association of genotypes of CYP1A1 T>C rs4646903, CYP1A1 A>G rs1048943, CYP2E1 T>A rs6413432, RAD51 G>C rs1801320, XRCC1 G>A rs25487, XRCC2 G>A rs3218536 and XRCC3 C>T rs861539 polymorphisms and survival after treatment (CRT) for cervical cancer." (PMID 35996502, 2022).
chronic lymphocytic leukemia (2 papers, 2012 to 2023). "In individuals with chronic lymphocytic leukemia/small lymphocytic lymphoma, the CYP2E1*07 (rs2070673) allele has been linked to a higher survival rate." (PMID 37047003, 2023).
epilepsy (2 papers, 2021 to 2022). A brain disorder characterized by episodes of abnormally increased neuronal discharge resulting in transient episodes of sensory or motor neurological dysfunction, or psychic dysfunction. "An experimental study showed an overexpression of CYP3A4, CYP2C9, and CYP2E1 in human brain microvascular endothelial cells of drug‐resistant patients with epilepsy while CYP2D6 and CYP2C19 were downregulated." (PMID 34560816, 2022).
gestational diabetes (2 papers, 2023). Carbohydrate intolerance first diagnosed during pregnancy. "A previous study reported that maternal gestational diabetes was associated with lower cord blood methylation level at the CYP2E1." (PMID 37596607, 2023). "This study aimed to determine if the genetic variations of 96-bp insertion/deletion (I/D) and C-1054T (rs2031920) in CYP2E1 were associated with the risk of gestational diabetes mellitus (GDM)." (PMID 37264354, 2023). "This suggested that the results were not driven by residual confounding due to gestational diabetes, a pregnancy condition that has been previously associated with CYP2E1 DNA methylation." (PMID 37596607, 2023).
glioblastoma (2 papers, 2023). The most malignant astrocytic tumor (WHO grade IV). "CYP2E1 increases in glioblastoma and is associated with poor prognosis." (PMID 37283464, 2023). "A pro‐GBM mechanism in which CYP2E1‐PPARγ‐STAT‐1/NF‐κB/STAT‐3/STAT‐6 axis fueled tumorigenesis by reprogramming M/Mφ and a newly developed CYP2E1 inhibitor, Q11, as a promising anti‐inflammatory agent for glioblastoma treatment is uncovered." (PMID 37283464, 2023).
Hyperinsulinemia (2 papers, 2015 to 2023). An increased concentration of insulin in the blood. "Hyperinsulinemia shifted the energy supply from glucose to ketone bodies, and the high ketone body concentration induced the overexpression of cytochrome P450 2E1 (CYP2E1)." (PMID 26358367, 2015).
invasive breast carcinoma (2 papers, 2012 to 2023). A carcinoma that infiltrates the breast parenchyma. "For the CYP2E1 region on chromosome 10, we identified three previously reported variants, but none were significantly associated with odds of invasive breast cancer in our sample." (PMID 37308906, 2023). "We also examined known variants and proxies with r2 ≥ 0.8 in four alcohol metabolism gene regions (ADH, CYP2E1, ALDH1, and ALDH2) in our meta-analysis results for main genetic effects on invasive breast cancer." (PMID 37308906, 2023).